CYP1A1 (cytochrome P450 family 1 subfamily A member 1)
Diseases named in the same sentence as CYP1A1 in open-access papers (continued):
Sharing a sentence is not in itself a finding about the gene and the disease.
heart failure (3 papers, 2010 to 2023). Inability of the heart to pump blood at an adequate rate to meet tissue metabolic requirements. "Studies had shown that CYP1A1 and AGTR2 are master regulators that are activated in heart failure." (PMID 38137330, 2023).
immunotoxicity (3 papers, 2012 to 2020). "Upon miR analysis, we observed several miRs that were downregulated (>1.5-fold) in thymocytes post-TCDD exposure thereby indicating that these miRs may be associated with regulation of AhR and CYP1A1 vis-a-vis immunotoxicity." (PMID 23024791, 2012). "Five genes (CD8A, CYP1A1, ITGAX, LYZ, and PTPRC) associated with immunotoxicity were among the most up‐regulated genes exposed to dose 1:8 indoor PM." (PMID 31883508, 2020).
inflammatory bowel disease (3 papers, 2018 to 2025). A spectrum of small and large bowel inflammatory diseases of unknown etiology. "Here, we explored role of CYP1A1 in UroA-mediated gut barrier and immune functions in regulation of inflammatory bowel disease (IBD)." (PMID 36159798, 2022). "This is not to say that induction of Cyp1a1 should be disregarded; indeed, a modest induction of Cyp1a1 in gene expression profiling sparked the discovery that the anti-inflammatory drug mesalamine ameliorates inflammatory bowel disease by interacting with the AHR10." (PMID 29379138, 2018).
ischemic stroke (3 papers, 2017 to 2020). A stroke disorder caused by obstruction of blood flow to the brain, due to thrombotic (local blood clot formation) or embolic (due to a blood clot or other material traveling from another site) event. "Recently, researches have also shown that CYP1A1 variants played a role in the development of ischemic stroke (IS) susceptibility in different populations, such as Turk, Indian and Chinese." (PMID 33046100, 2020). "In conclusion, CYP1A1 was shown to be significantly associated with ischemic stroke in certain clinical studies; however, further investigation is required to verify this association." (PMID 31638212, 2019).
larynx cancer (3 papers, 2020 to 2025). A primary or metastatic malignant neoplasm involving the larynx. "They found that subjects presenting SNPs for CYP1A1 rs1048943 and rs4646903 had an increased risk of larynx cancer." (PMID 32882964, 2020). "CYP1A1 rs4646903 T>C polymorphisms were detected in 100% of cases of larynx cancer and 17.39% of healthy subjects (p > 0.001)." (PMID 32882964, 2020). "In the present study, all 80 (100%) of the cases of larynx cancer presented rs4646903 CYP1A1 T>C polymorphism (p > 0.001)." (PMID 32882964, 2020). "The aim of this study was to determine the presence of SNPs responsible for the loss of function of GSST1, GSTM1, CYP1A1 and CYP1A2 genes, as markers of risk, in a group of smokers and drinkers with larynx cancer." (PMID 32882964, 2020). "Conclusions: patients with larynx cancer present more gene GSTM1 and GSTT1 null polymorphisms, and CYP1A1 rs4646903 T>C polymorphisms." (PMID 32882964, 2020). "As results patients with larynx cancer present more gene GSTM1 and GSTT1 null polymorphisms, and CYP1A1 rs4646903 T>C polymorphisms." (PMID 32882964, 2020). "Objective: to compare the presence of null SNPs in genes GSTM1, GSTT1, and CYP1A1 rs 4646903 T>C, and CYP1A1–2 RS1048943 A>G in patients with hypopharyngeal and larynx cancer with a healthy control group." (PMID 32882964, 2020). "As for CYP1A1 rs1048943 A>G polymorphism, for CYPA1A2 genotype, GG polymorphisms were detected in 80% of larynx cancer cases although without statistically significant difference (p = 0.075)." (PMID 32882964, 2020).
liver fibrosis (3 papers, 2014 to 2022). "We also measured hepatic expression of genes involved in detoxification/drug metabolism (Cyp1a1, Cyp1b1), inflammation (Il1b) and hepatic fibrosis (Col1a1)." (PMID 35788891, 2022). "Moreover, CYP1A1, ODC1 and MAOB may be potential targets related to the anti-liver fibrosis effects of dehydrocarptin, tetrahydropalmatine and palmatine, respectively." (PMID 36676934, 2022). "Furthermore, CYP1A1, ODC1 and MAOB comprise the intersection of TACS targets, metabolic pathway targets and disease-related targets, and dehydrocavidine, tetrahydropalmatine and palmatine are considered as potential active compounds for CCl4-induced liver fibrosis therapy." (PMID 36676934, 2022).
neuroblastoma (3 papers, 2009 to 2024). Neuroblastoma (NB) is the most common solid, extracranial childhood tumor. "Similar effects on CYP1A1 expression in neuroblastoma UKF-NB-3 and UKF-NB-4 cell lines were detected when cells were treated for 48 hours with TSA." (PMID 21217856, 2009). "The different effects of VPA and TSA were found on expression of CYP1A1, 1B1 and 3A4 enzymes in individual neuroblastoma cells tested in the study." (PMID 21217856, 2009). "Expression of CYP1A1 protein in neuroblastoma UKF-NB-3 and UKF-NB-4 cells was elevated by increasing concentrations of VPA and/or TSA in a dose-dependent manner." (PMID 21217856, 2009). "The complete inhibition of CYP1A1 induction in neuroblastoma cells and cyp1a in zebrafish by the AHR antagonist GNF-351 strongly supports the hypothesis that AHR activation is instrumental for EDA-induced CYP pathway stimulation." (PMID 38672460, 2024). "The finding that VPA and TSA are capable of inducing and depressing CYP enzyme expression in neuroblastoma cells (CYP1A1, 1B1 and 3A4 tested in our work) might have great importance." (PMID 21217856, 2009). "Using targeted transcriptomic analysis and qPCR, we observed a significant increase in the expression of genes related to the AHR pathway (CYP1A1, CYP1B1, AHRR) in mouse OPCs and human neuroblastoma SH-SY5Y cells after treatment with EDA." (PMID 38672460, 2024). "Using Western blot analysis with antibodies raised against CYP1A1, 1B1 and 3A4, the effects of VPA and TSA on protein expression levels of these enzymes were analyzed in the tested neuroblastoma cell lines." (PMID 21217856, 2009).
pharyngeal cancers (3 papers, 2008 to 2022). "In the present case-controlstudy, we aimed to examine the relationship between the CYP1A1 Ile/Val, exon 4 mEH(139 Arg → His), and GSTM1 nullgenetic polymorphism and the risk of oral and pharyngeal cancers, investigatingalso the association with smoking, drinking, and the gene-gene interactions." (PMID 19259333, 2008).
renal carcinoma (3 papers, 2015 to 2020). A carcinoma arising from the epithelium of the renal parenchyma or the renal pelvis. "The CYP1A1 polymorphisms might play an important role in the etiology of renal cancer." (PMID 26537097, 2015).
schizophrenia (3 papers, 2020 to 2025). A major psychotic disorder characterized by abnormalities in the perception or expression of reality. "In summary, an inverse connection between CYP1A1 and miR-21; CYP1B1 with miR-27b and miR-200c; and CYP1A2 with miR-122 points to a miRNA-CYP enzyme regulatory network in schizophrenia that can be readily detected in the blood." (PMID 39812050, 2025). "Additionally, miR-27b, miR-200c, miR-21 and miR-122 and miR-132 may serve as ideal theranoMiRNAs in schizophrenia, particularly when analysed in conjunction with CYP1A2, CYP1B1 and CYP1A1 activities." (PMID 39812050, 2025).
ulcerative colitis (3 papers, 2016 to 2020). An inflammatory bowel disease involving the mucosal surface of the large intestine and rectum. "Furthermore, CYP1A1, an enzyme in the phase I of the reactions which helps in the excretion of endogenous (e.g. steroids) and exogenous (e.g. drugs) substances, was lower in the colonic enterocytes of patients suffering from Crohn’s disease and ulcerative colitis." (PMID 33362778, 2020).
wasting syndrome (3 papers, 2012 to 2018). "Further studies will clarify the relation of cPLA2α/AA/SRC, CYP1A1, and Tiparp pathways in TCDD-induced weight loss or wasting syndrome." (PMID 29043426, 2018). "Neither wasting syndrome nor CYP1A1 induction in the fetal brain caused through the activation of aryl hydrocarbon receptor (AhR) could be attenuated by LA." (PMID 22911699, 2012).
actinic keratosis (2 papers, 2018 to 2020). A precancerous lesion of the skin composed of atypical keratinocytes. "Immunohistochemical analysis was used to detect the expression of AHR, CYP1A1, EGFR, and Ki-67 in 10 actinic keratosis (AK) cases, 10 Bowen disease (BD) cases, 20 cutaneous squamous cell carcinoma (cSCC) cases and 20 normal skin samples." (PMID 30144817, 2018).
acute kidney injury (2 papers, 2019 to 2022). Sudden and sustained deterioration of the kidney function characterized by decreased glomerular filtration rate, increased serum creatinine or oliguria. "Pretreatment with tanshinone I has shown protective effects against AA-induced acute kidney injury, notably through an increase in AA metabolization by CYP1A1." (PMID 35409033, 2022). "Historically, human exposure to high affinity AhR ligand, TCDD (which is not metabolized by Cyp1A1) displayed severe adverse events such as appearance of cysts, eruptions, pustules, and erythema as well as life threatening manifestations including liver, renal failures, myocardial degeneration." (PMID 30626868, 2019).
acute leukemia (2 papers, 2012). A clonal (malignant) hematopoietic disorder with an acute onset, affecting the bone marrow and the peripheral blood. "The overall data indicated a significant association of CYP1A1 Ile462Val polymorphism with acute leukemia risk (Val/Val vs Ile/Ile OR = 1.49; 95% CI = 1.11–1.98; dominant model: OR = 1.26; 95% CI = 1.05–1.51; recessive model: OR = 1.38; 95% CI = 1.04–1.83)." (PMID 23056546, 2012). "Meta-analyses evaluating the association of CYP1A1 Ile462Val variation with acute leukemia were carried out." (PMID 23056546, 2012). "A number of published studies have been conducted on the relationship between CYP1A1 Ile462Val polymorphism and acute leukemia risk." (PMID 23056546, 2012). "The results of the present study suggest that CYP1A1 Ile462Val polymorphism might be a low-penetrant risk factor for acute leukemia." (PMID 23056546, 2012). "In summary, the results of the present meta-analysis suggest that variant Val allele of CYP1A1 Ile462Val polymorphism might have an association with excess acute leukemia risk." (PMID 23056546, 2012). "For the overall data, the results showed that CYP1A1 Ile462Val might have a marked correlation with increased acute leukemia risk." (PMID 23056546, 2012). "Distribution of CYP1A1 Ile462Val genotype among acute leukemia cases and controls included in the meta-analysis." (PMID 23056546, 2012). "Recently, a meta-analysis regarding the association of CYP1A1 MspI variation with childhood acute leukemia failed to reveal a significant association." (PMID 23056546, 2012). "The issue of whether the CYP1A1 Ile462Val polymorphism is a risk factor for acute leukemia has not been clearly addressed." (PMID 23056546, 2012).
acute myeloid leukemia (2 papers, 2012 to 2024). Acute myeloid leukemia (AML) is a group of neoplasms arising from precursor cells committed to the myeloid cell-line differentiation. "A growing body of literature has been devoted to the association of CYP1A1 MspI polymorphism with acute myeloid leukemia (AML)." (PMID 22846179, 2012).
adenoma (2 papers, 2014 to 2018). A neoplasm arising from the epithelium. "To explore this possibility we assessed the effects of Brg1 loss on Wnt-driven adenoma formation by driving recombination of the floxed Apc and Brg1 alleles with the Tg(Cyp1a1-cre/ESR1)1Dwi transgene, further abbreviated as AhCreERT." (PMID 25010414, 2014).
adenomyosis (2 papers, 2022 to 2023). The growth of endometrial tissue inside the muscular wall of the uterine corpus. "Patients with adenomyosis have increased frequency of the C allele in the T/C and C/C genotypes of the CYP1A1 gene, A allele in the C/A and A/A genotypes of the CYP1A2 gene, and the T allele in the C/T and C/C genotypes of the CYP19 gene compared with women without adenomyosis." (PMID 35887822, 2022). "There is an increased frequency of the C allele in the T/C and C/C genotypes of the CYP1A1 gene, A allele in the C/A and A/A genotypes of the CYP1A2 gene, and the T allele in the C/T and C/C genotypes of the CYP19 gene in patients with adenomyosis." (PMID 37763670, 2023).
alcoholic liver diseases (2 papers, 2021 to 2024). A disorder caused by damage to the liver parenchyma due to alcohol consumption. "Alcoholic liver disease and primary biliary cholangitis were involved in the most prominent changes in the protein abundances, with downregulation of 6 (CYP1A2, CYP2C8, CYP2D6, CYP2E1, CYP3A4, UGT2B7) and 5 (CYP1A1, CYP2B6, CYP2C8, CYP2E1, CYP3A4) significantly downregulated enzymes, respectively." (PMID 34575411, 2021).
asthma (2 papers, 2008 to 2024). "In a murine model of TDI asthma, challenging with TDI resulted in an increased expression of CYP1A1 in the lung." (PMID 18447907, 2008). "However, the role of CYP1A1 for TDI-asthma was unclear, since TDI seemed to partly inhibit the activity of CYP1A1." (PMID 18447907, 2008).
autism (2 papers, 2021 to 2024). Persistent deficits in social interaction and communication and interaction as well as a markedly restricted repertoire of activity and interest as well as repetitive patterns of behavior. "Homozygous (TT) slow genotype in the CYP1A1 and MAO variants was observed in two cases of autism patients." (PMID 39148948, 2024). "Meta-analysis studies across two prospective pregnancy cohorts showed that the CYP1A1 gene expression was downregulated in umbilical cord blood from subjects with autism, suggesting its involvement in ASD etiology." (PMID 34502168, 2021). "This section summarizes the most recent human and experimental studies and evidence for the potential role of AhR and its regulated genes, CYP1A1, CYP1B1, and CYP1A2 on autism development." (PMID 34502168, 2021). "What supports this possibility is that AhR and its regulated genes, CYP1A1, CYP1A2, and CYP1B1, are highly and constitutively expressed in the placenta, which may be activated by exposure to environmental toxicants during pregnancy and, hence, increase the incidence of autism." (PMID 34502168, 2021).
Bladder Tumors (2 papers, 2013 to 2015). "From the CPN 50 directly relevant nodes have been retrieved for Capecitabine including the gene CYP1A1, from which “Urinary Bladder Neoplasms” have been identified subsequently." (PMID 25729430, 2015). "The results of our analysis corroborate with these findings, given that CYP1A1 and CYP1B1 mRNA transcripts were elevated in 80% and 60% of colon and in 65% of bladder tumors respectively." (PMID 24358191, 2013). "Our observations clearly indicate that CYP1A1 and CYP1B1 are overexpressed in colon and bladder tumors." (PMID 24358191, 2013). "CYP1A1 and CYP1B1 were differentially overexpressed in colon and bladder tumors." (PMID 24358191, 2013).
candidiasis (2 papers, 2020 to 2024). Infection with the organism Candida. "For this purpose, we evaluated the expression of genes downstream of AhR, such as cytochrome P450 family 1 subfamily A member 1 (Cyp1a1) and subfamily B member 1 (Cyp1b1) and Il22 in the lungs and colons of mice with aspergillosis and candidiasis, respectively." (PMID 38534388, 2024).
cerebral infarction (2 papers, 2019 to 2020). An ischemic condition of the brain, producing a persistent focal neurological deficit in the area of distribution of the cerebral arteries. "Analysis of gene-gene interactions showed that the GSTM1 null genotype increased the cerebral infarction risk in carriers of the CYP1A1 C allele (P=0.015; OR, 1.47; 95% CI, 1.08–2.00)." (PMID 31638212, 2019). "Therefore, cerebral infarction may be associated with vascular inflammation and oxidative stress; AhR downstream genes, such as CYP1A1, GSTT1 and GSTM1, may serve important roles in the pathogenesis." (PMID 31638212, 2019). "A significantly larger number of patients with cerebral infarction had the CYP1A1 gene 3′-flanking region (T6235C) compared with the controls (P=0.017; OR, 1.44; 95% CI, 1.07–1.94)." (PMID 31638212, 2019).
diabetic cardiomyopathy (2 papers, 2022 to 2025). Diabetic cardiomyopathy is a disorder of the heart muscle in people with diabetes. "The salient findings from the present study support that Cyp1a1, a significantly upregulated DEG, has the highest connectivity in the PPI interaction network among the top five hub genes (Cyp1a1, Cyp2e1, Col1a1, Col3a1, Col1a2) to affect the cardiac function in STZ-induced diabetic cardiomyopathy." (PMID 35387435, 2022).
epilepsy (2 papers, 2017 to 2018). A brain disorder characterized by episodes of abnormally increased neuronal discharge resulting in transient episodes of sensory or motor neurological dysfunction, or psychic dysfunction. "Genetic contribution of CYP1A1 alleles on treatment outcome in people with epilepsy was studied in an Indian population." (PMID 28082152, 2018). "In particular, the variant rs2606345 (resulting in reduced CYP1A1 expression) was associated with poor response to first-line AEDs in Indian women with epilepsy." (PMID 28082152, 2018).
fetal growth restriction (2 papers, 2015 to 2023). A fetus that does not grow beyond the 10th percentile of conventionally accepted weight for gestational age. "Suter and colleagues observed that maternal tobacco use is associated with alterations in promoter methylation of placental CYP1A1 gene and that these changes are correlated with CYP1A1 expression and fetal growth restriction." (PMID 25648174, 2015). "CYP1A1 protein is involved in the synthesis of cholesterol, steroids, and lipids, as well as in drug metabolism; elevated CYP1A1 protein levels have been previously associated with premature birth, intrauterine growth restriction, and placental abruption, but not PE." (PMID 37063698, 2023).
fibrosarcoma (2 papers, 2019 to 2025). A malignant mesenchymal fibroblastic neoplasm affecting the soft tissue and bone. "Furthermore, reduced CYP1A1 expression in MΦs attenuated tumor formation in the MCA-induced fibrosarcoma model." (PMID 30615637, 2019). "Consequently, reduced CYP1A1 expression in mice with a myeloid HIF-1α knockout developed fewer tumors in the MCA-induced fibrosarcoma model." (PMID 30615637, 2019).
hyperandrogenism (2 papers, 2022 to 2023). Excessive secretion of androgens from the adrenal glands or gonads. "The results of our study showed that in PCOS patients, the significant positive correlations were obtained for Ahr, Arnt, Cyp1A1, and Cyp1B1 with incidence of clinical hyperandrogenism." (PMID 36368943, 2022). "Moreover, we showed that there is a correlation between clinical hyperandrogenism and follicular testosterone levels and Cyp1A1, and Cyp1B1 mRNA levels." (PMID 36368943, 2022). "Also, the significant positive correlations were obtained for Ahr, Arnt, Cyp1A1, and Cyp1B1 with incidence of clinical hyperandrogenism and FFT level." (PMID 36368943, 2022). "In women with PCOS, a correlation between elevated levels of AhR, ARNT, CYP1A1, and CYP1B1 genes and clinical hyperandrogenism, follicular fluid testosterone levels, and disturbed folliculogenesis was observed." (PMID 37572199, 2023).
influenza (2 papers, 2021 to 2025). An acute viral infection of the respiratory tract, occurring in isolated cases, in epidemics, or in pandemics; it is caused by serologically different strains of viruses (influenzaviruses) designated A, B, and C, has a 3-day incubation period, and usually lasts for 3 to 10 days. "Following influenza infection, Cyp1a1 expression increased significantly in vehicle-exposed mice but failed to increase in PM-exposed mice." (PMID 34906172, 2021). "We determined the expression of Cyp1a1, a marker for AhR activation, in PM-exposed and influenza-infected mice." (PMID 34906172, 2021).